DGAT1 (diacylglycerol O-acyltransferase 1)
Diseases named in the same sentence as DGAT1 in open-access papers (continued):
Sharing a sentence is not in itself a finding about the gene and the disease.
metabolic disorders (15 papers, 2011 to 2024). "Furthermore, it was unclear whether gut DGAT1 deficiency is sufficient to confer metabolic benefits, and by inference, whether gut-selective DGAT1 inhibitors would be efficacious in treating metabolic disorders." (PMID 23336002, 2013). "DGAT1 has emerged as an attractive druggable target for certain metabolic disorders (Chen and Farese, 2005, DeVita and Pinto, 2013)." (PMID 31786011, 2020). "Inhibition of Diacylglycerol O-acyltransferase 1 (DGAT1) has been a mechanism of interest for metabolic disorders." (PMID 24558447, 2014). "We also indicated that the intestine-targeted DGAT1 inhibitor improved metabolic disorders in DIO mice." (PMID 25405858, 2014). "The current study suggests that targeting DGAT1 to enhance postprandial gut hormone secretion requires maximal inhibition, and suggests combination with DPP-4i as a potential strategy to develop DGAT1 inhibitors for treatment of metabolic diseases." (PMID 23336002, 2013). "Based on the improved metabolic function observed in Dgat1 knockout mice, it was proposed that DGAT1 inhibitors could be an effective therapeutic strategy to counter metabolic disorders." (PMID 36878315, 2023). "Is DGAT1 a potential target to treat metabolic disorders, including cardiovascular disease?" (PMID 32882484, 2020). "However, the effects of DGAT1 inhibition or DGAT1 silencing in human hepatocytes are unknown, although DGAT1 inhibitors have been developed and are undergoing clinical trials for the treatment of metabolic diseases." (PMID 26493024, 2016). "As the metabolic phenotypes of DGAT1 null mice are lost when DGAT1 is reintroduced into the intestine, we raised a hypothesis that the intestine-targeted DGAT1 inhibitor would improve metabolic disorders with minimizing the adverse effect that may be driven by systemic DGAT1 inhibition." (PMID 25405858, 2014). "DGAT1 inhibition in the whole body may reduce excessive triglyceride deposition in the non-adipose tissues including the skeletal muscle, resulting in amelioration of metabolic disorders." (PMID 25405858, 2014). "As a result, we have found that the predominantly intestine-targeted DGAT1 inhibitor attenuates metabolic disorders without inducing skin aberrations." (PMID 25405858, 2014). "Since DGAT1 catalyzes this triglyceride rearrangement, the improvement of metabolic disorders observed in DGAT1 null mice seems to be derived from lack of DGAT1 activity in the intestine." (PMID 25405858, 2014).
neurodegenerative disease (2 papers, 2022 to 2025). A disorder of the central nervous system characterized by gradual and progressive loss of neural tissue and neurologic function. "Targeting proteins such as fatty acid synthase (FASN), diacylglycerol O-acyltransferase 1 (DGAT), and ATP-citrate lyase (ACLY) has shown promise in alleviating some symptoms of neurodegenerative diseases." (PMID 41373990, 2025). "Targeting FASN, Diacylglycerol O-acyltransferase 1 (DGAT), ATP-citrate lyase (ACLY) and maybe other important proteins appears to alleviate neurodegenerative diseases to some extent." (PMID 36588702, 2022).
genetic disease (1 paper, 2025). "DGAT‐1 deficiency is a rare genetic disease which leads to congenital diarrhea and is especially dangerous in infancy." (PMID 40386326, 2025).
heart disease (1 paper, 2025). "While not a predefined variable for analysis, we observed that patients in the late achievement group often had more complex underlying conditions and multiple comorbidities, such as septic shock with multiorgan failure, DGAT1 mutation, and complex heart disease." (PMID 41402769, 2025).
skeletal dysplasia (1 paper, 2017). Any Mendelian diseases that affects growth and development of the skeleton. "For example, the allele in the Acyl-CoA:diacylglycerol acyltransferase 1 (DGAT1) increases milk fat content and decreases milk yield in dairy cattle, and the risk allele FYVE, RhoGEF and PH domain-containing protein 3 (FGD3) of skeletal dysplasia increases carcass weight." (PMID 29132308, 2017).
DGAT1 also shares sentences with these, for which no sentence is quoted: Hyperglycemia (2 papers); metabolic dysfunction-associated steatotic liver disease (2); abetalipoproteinemia (1); acne (1); age (1); Anxiety (1); atrial fibrillation (1); bacterial infection (1); bladder cancer (1); Cachexia (1); cardiac hypertrophy (1); cardiovascular disease (1); celiac disease (1); cervical cancer (1); Charcot-Marie-Tooth disease (1); Cirrhosis (1); colitis (1); colorectal carcinoma (1); cutaneous melanoma (1); depression (1); dyskeratosis congenita (1); familial chylomicronemia syndrome (1); fish eye disease (1); Fundus dystrophy (1); gastrointestinal tumor (1); Granuloma (1); hypobetalipoproteinemia (1); Immunodeficiency (1); Impaired glucose tolerance (1); intestinal lymphangiectasia (1).
A further 16 diseases each share a sentence with DGAT1 in 1 paper.